HMGB1 (high mobility group box 1)
Diseases named in the same sentence as HMGB1 in open-access papers (continued):
Sharing a sentence is not in itself a finding about the gene and the disease.
infection (continued). "On the contrary, patients with severe CCHF indicated statistically significantly higher level of HMGB1 than patients with the mild infection, although it was shown that CCHFV suppresses IFN-β promoter mediated gene expression." (PMID 27348219, 2016). "Many studies reveal the essential roles of HMGB1 in modulating tissue damage and inflammation during sterile injury and infection." (PMID 27634894, 2016). "Six hours after infection, gene changes involved pathways such as HMGB-1, interleukin (IL)-2, IL-6, IL-8, janus kinase/signal tranducer and activator of transcription (JAK/STAT), interferon, and ERK 5 signaling (P < 0.01)." (PMID 27119120, 2016). "Similar to their inhibitory effects on HMGB1 acetylation/release during the infection, GAR, RES, and BAY treatment decreased the acetylation/release of HMGB1 caused by PEDV-N overexpression." (PMID 27634894, 2016). "Similar to the study on Dengue virus, our data also showed that HMGB1 was translocated from the nucleus into the cytoplasm and released into the extracellular space at the early stage of infection." (PMID 27634894, 2016). "Anti-TNF-α agents and/or anti-HMGB-1 agents improved survival rates when administered at a later stage of infection, and it became clear that efficacy was dependent on time of administration." (PMID 27556404, 2016). "HMGB1 was originally discovered as a 25 kDa DNA-binding protein that participates in many nuclear functions and, triggered by infection and proinflammatory stimuli, HMGB1 can be released extracellularly and act as a proinflammatory mediator." (PMID 26871575, 2016). "HMGB1 is a multifunctional protein that is involved in transcription control, DNA repair and response to infection and inflammation." (PMID 27537498, 2016). "Convergence in TNF-α count occurred at approximately 14 days after infection, earlier than convergence in HMGB-1 count in innate immunity." (PMID 26446682, 2015). "In 1999, cytosolic HMGB1 was discovered to be a proinflammatory mediator that is secreted by activated macrophages in response to injury, infection or other inflammatory stimuli." (PMID 26317615, 2015). "Compared to Persistent Infection observed in innate immunity, the activated neutrophil count and HMGB-1 count converged toward 0 at approximately 25 days (600 hrs) after infection." (PMID 26446682, 2015). "In order to study the contribution of HMGB1 to the evolution of TB during late progressive phase, specific blocking antibodies were administered after two months of infection and during one month." (PMID 26201072, 2015). "Both CXCL8 and HMGB1 were significantly increased already after eight hours of infections with all four strains." (PMID 26601609, 2015). "HMGB1 was blocked with specific antibodies or recombinant HMGB1 was administered during early or late infection." (PMID 26201072, 2015). "While CXCL8 levels were increasing over time, the maximum of HMGB1 was reached already at 8 hours post-infection, indicating that the cell and tissue injury occurs at the early stage of infection." (PMID 26601609, 2015). "At day 7 to 21 the oxidized HMGB1 was predominant, while during late infection only the reduced form was seen." (PMID 26201072, 2015). "Targeting the translocation, release, and activity of HMGB1 can limit inflammation and reduce tissue damage during infection and sterile inflammation." (PMID 25904867, 2015). "Following infection with these adenoviruses, the levels of exogenous HMGB1 and SIRT1 proteins were similar in the presence and absence of LPS." (PMID 26522327, 2015). "Suppression of NRF2 or HO-1 significantly increases oxidative injury and HMGB1 release, whereas upregulation of HO-1 inhibits HMGB1 release in infection." (PMID 25904867, 2015). "As a ubiquitous nuclear protein, HMGB1 can be passively released from pathologically damaged cells, thereby converging infection and injury on commonly dysregulated inflammatory responses." (PMID 26257917, 2015).
infection (continued). "After one week and until two months of infection there was a constant concentration of HMGB1 in BALF, from 10 to 15ng/ml." (PMID 26201072, 2015). "Blocking HMGB1 during early infection produced significant decrease of bacilli burdens and high production of pro-inflammatory cytokines, while the opposite was seen when HMGB1 was administered." (PMID 26201072, 2015). "The quantification of HMGB1 in BALF by ELISA showed the highest concentration on day one of infection, followed by a sharp decrease on day three." (PMID 26201072, 2015). "Alveolar and interstitial macrophages also showed HMGB1 immunostaining during early infection and progressively increased, being 10 +/- 3% on day one to 30+/-5% on day 60 of infection in the pneumonic areas; occasional positive cells were found in granulomas." (PMID 26201072, 2015). "Recent studies have reported endogenous DAMPs (mtDNA, HMGB1) released as a consequence of tissue injury or infection appear to be promising biomarkers; however, the evidence supporting their role is still limited." (PMID 26502877, 2015). "Since the discovery of HMGB1 in 1973, the multi-faceted HMGB1 has recently been identified as an important mediator of infection and sterile inflammation, which has initiated a new field of translational medicine for targeting HMGB1 in disease." (PMID 25904867, 2015). "In a previous study, was demonstrated that the infection in-vitro of macrophages and monocytes with mycobacteria induced HMGB1 release, and some mycobacterial proteins such as 65kD HSP induced its maximum release." (PMID 26201072, 2015). "In response to infections and injuries, however, HMGB1 is secreted from activated immune cells or passively released from injured cells." (PMID 25821489, 2015). "In comparison with control mice, animals that received HMGB1 blocking antibodies showed higher inflammation in the alveolar-capillary interstitium during the first week of infection." (PMID 26201072, 2015). "The SDSE infection, in both infected skin tissue and patient biopsies, resulted in high levels of the inflammatory markers CXCL8 and HMGB1, the latter of which is also associated with necrosis." (PMID 26601609, 2015). "In comparison with control animals that received human albumin, mice that received HMGB1 by the intratracheal route showed a significant increase of bacilli burdens after one week of infection." (PMID 26201072, 2015). "If dysregulated, the excessive HMGB1 release adversely contributes to the pathogenesis of infection- and injury-elicited inflammatory diseases." (PMID 26257917, 2015). "SSAO facilitates leukocyte accumulation during inflammation, and HMGB1 levels increase in serum during sterile tissue injury and infection." (PMID 26633364, 2015). "Our findings suggest that anti-HMGB1 antibodies strategies warrant further evaluation as a therapeutic to reduce infection and MODS after trauma." (PMID 25709155, 2015). "Excessive HMGB1 secretion/release adversely contributes to the pathogenesis of infection- and injury-elicited inflammatory diseases." (PMID 25821489, 2015). "Blocking HMGB1 activity or administrated it in high amounts during late infection worsening the disease." (PMID 26201072, 2015). "Here, we showed that PAO1 infection induced acetylation of the epsilon-amine groups of lysine residues in HMGB1 and nuclear translocation of HMGB1." (PMID 24923305, 2014). "Outside the cell, HMGB1 functions as a proinflammatory responder to exogenous factors (e.g., infection and stress)." (PMID 25469638, 2014). "To further investigate the effect of FIP200 on the expression of HMGB1 in MH-S cells, we performed a Co-IP assay and found an interaction between FIP200 and HMGB1 following PAO1 infection." (PMID 24923305, 2014). "Analyses of tissue biopsies from patients with varying severity of S. pyogenes infections revealed a significant correlation between increased HMGB1 and severity of tissue infection." (PMID 24524027, 2014).
infection (continued). "Silencing FIP200 impaired the translocation of HMGB1 to cytosol of MH-S cells and almost abolished acetylation of HMGB1 during PAO1 infection." (PMID 24923305, 2014). "Extracellular HMGB1 is a multifunctional cytokine that contributes to the process of infection, injury, inflammation, apoptosis, and immune responses by binding to specific cell-surface receptors." (PMID 25284457, 2014). "We next examined the functional role of FIP200 on HMGB1 translocation and also found that FIP200 knockdown in MH-S cells inhibited HMGB1 translocation from nuclei to cytoplasm upon PAO1 infection using immunocytochemistry staining." (PMID 24923305, 2014). "This was further strengthened by in vitro infection of human monocyte-derived macrophages with S. pyogenes resulted in a release of HMGB1." (PMID 24524027, 2014). "During infection, HMGB1 is translocated from the nucleus to the cytoplasm and is subsequently released into the extracellular milieu by HCV or HBV infection." (PMID 25356587, 2014). "NK cell transfer in newborn mice led to decreased mRNA level of HMGB1 compared to that of the control on day 7 post RRV-infection." (PMID 24651485, 2014). "To elucidate the functional role of FIP200 on HMGB1 translocation, we transfected MH-S cells with a myc-FIP200 plasmid and observed that FIP200 overexpression facilitated the cytosol translocation of HMGB1 from nuclei upon PAO1 infection." (PMID 24923305, 2014). "As shown in this study, both newborn and adult macrophages can release HMGB1 after 24 hours after RRV infection." (PMID 24651485, 2014). "During infection or injury, activated immune cells and damaged cells release HMGB1 into the extracellular space, where HMGB1 functions as a pro-inflammatory mediator and contributes to the pathogenesis of inflammatory diseases." (PMID 25127031, 2014). "Microscopy analyses revealed HMGB1 in all investigated biopsies, and notably, the levels correlated with severity of infection." (PMID 24524027, 2014). "After RRV-infection in cholangiocytes or HMGB1 stimulation of NK cells, increased activation was noted in NK cells compared to controls (p<0.05 or p<0.01)." (PMID 24651485, 2014). "Taken together, the findings provide the first in vivo evidence that HMGB1 is abundant at the local site of severe bacterial STIs and its levels correlated to severity of infections; hence, indicating its potential value as a biomarker for tissue pathology." (PMID 24524027, 2014). "The mRNA level of HMGB1 in the newborn group increased from day 1 through day 7; while the mRNA level of HMGB1 was increased by approximately 30% in the 7 day group and by 50% in the adult group on day 3 compared to those on day 1 post-infection." (PMID 24651485, 2014). "To mechanistically elucidate translocation of HMGB1 during PAO1 infection, we fractioned nuclear compartment from cytoplasm using a commercial kit (NE-PER Nuclear And Cytoplasmic Extraction Reagents)." (PMID 24923305, 2014). "Damage-associated molecular patterns (DAMP), such as the high-mobility group protein B1 (HMGB1), are detected at above normal levels in blood serum only after 72 h post-infection." (PMID 25566509, 2014). "For example, higher amounts of HMGB1 were found in biopsies from severe STIs as compared to erysipelas, as well as in the center as compared to distal site of infection." (PMID 24524027, 2014). "Fip200 deficiency significantly reduced the expressions of HMGB1, RAGE and TLR4 in lung tissue after PAO1 infection." (PMID 24923305, 2014). "At 6 hours post infection, anti-HMGB1 treatment reduced total pathology scores (P <0.01 versus Wt mice), which was mostly caused by a reduction of lung edema compared to control antibody treatment." (PMID 24342460, 2013). "In this review, we have discussed the diagnostic and therapeutic potential of nuclear antigens (histone H1 and HMGB1) and the corresponding antinuclear Abregs on infection, injury, inflammation, and transplant rejection." (PMID 23690821, 2013).
infection (continued). "After infection, both bacteria produced endotoxins and various cytokines released by activated monocytes/macrophages such as TNFα, IL1β, IFNγ etc. can promote HMGB1 translocation from nucleus to cytoplasmic organelles." (PMID 22947457, 2012). "High mobility group box 1 (HMGB1) protein is released from cells as a pro-inflammatory cytokine in response to an injury or infection." (PMID 22860034, 2012). "HMGB1 was released from DV-infected K562 cells into the extracellular milieu in a multiplicity of infection (M.O.I.)-independent manner and its release can be inhibited by the addition of 1–5 mM of ethyl pyruvate (EP) in a dose-dependent manner." (PMID 22860034, 2012). "As K562 cells showed HMGB1 release upon DV-infection, we went on to investigate if DV-infection of PBM cells from healthy blood donors showed similar HMGB1 translocation." (PMID 22860034, 2012). "siRNA gene silencing of PCAF has resulted in the inhibition of HMGB1 release into the extracellular milieu during DV-infection, suggesting that DV induces HMGB1 release through acetylation." (PMID 22860034, 2012). "Cytosolic fractions of DV-infected cells contain 90% more HMGB1 than nuclear fractions, suggesting that HMGB1 migrates from the nucleus to the cytoplasm upon DV-infection." (PMID 22860034, 2012). "HMGB1 was also observed in the cytoplasm of DV-infected K562 cells hence, suggesting that the export of HMGB1 from the nucleus to the cytoplasm upon DV infection." (PMID 22860034, 2012). "HMGB1 protein can be released by cells into the extracellular milieu to function as a proinflammatory cytokine in response to injury, infection and inflammation." (PMID 22860034, 2012). "Immunoblotting was used to detect HMGB1 in culture supernatants of macrophages following 24 hr infection with KIM5 or KIM5 expressing YopJC172A." (PMID 22563435, 2012). "In peripheral blood, HMGB1 has been recently demonstrated to be a cytokine secreted by activated immune cells and mediate the response to infection, injury and inflammation." (PMID 21915243, 2011). "A marked decrease in HMGB1 transcription was observed as early as 3 h post-infection (pi) and reached 98% after 48 h." (PMID 21283827, 2011). "HMGB1 release has previously been reported during in vitro infection with RNA viruses such as Dengue virus or HIV-1." (PMID 21283827, 2011). "Despite a transcriptional shutdown of HMGB1 gene expression during infection, the intracellular pool of HMGB1 protein remained unaffected, indicating its remarkable stability." (PMID 21283827, 2011). "Nevertheless, virus-induced necrosis still occurred later during the infection, promoting massive release of HMGB1." (PMID 21283827, 2011). "Similar trend in HMGB1 up-regulation has been observed after 48 h of treatment with stimuli mimicking infection." (PMID 21915243, 2011). "More recently, HMGB1 has been demonstrated to be a crucial cytokine that mediates the response to infection, injury and inflammation." (PMID 21915243, 2011). "In the presence of HSV-2, HMGB1 gradually moved from the cytosol and transiently concentrated in the nucleus, suggesting that it was retained on chromatin early after infection." (PMID 21283827, 2011). "When it is actively secreted by inflammatory cells or passively released from necrotic cells, HMGB1 mediates the response to infection, injury and inflammation, inducing dendritic cells maturation and T helper-1-cell responses." (PMID 21915243, 2011). "In a previous study, we reported that NK∶DCHIV cognate interaction under conditions of DC maturation (ratio 1∶5) resulted in a strong increase in HIV-1 viral replication in DCs (detected at day 3 after infection), that was mediated by HMGB1." (PMID 20419158, 2010). "On the other hand, the pro-inflammatory chromatin binding protein, HMGB1, was detected as early as 2 h after infection in the supernatant of the IFNγ-induced, T. gondii infected cells but not in the supernatants of the cycloheximide and TNFα-treated cells." (PMID 19197351, 2009).
infection (continued). "This is likely due to the spontaneous release of HMGB1 by iDC, shown here and previously reported, which was preserved following their infection with HIV-1." (PMID 18974890, 2008). "Elevated levels of HMGB1, LBP and PCT were associated with the presence of infection and with the presence of bacteraemia in patients with community-acquired infections." (PMID 17625012, 2007). "High mobility group box 1 protein (HMGB1), a nuclear protein, is a critical cytokine that mediates the response to infection, injury, and inflammation." (PMID 18288272, 2007). "pylori infection by inhibiting ferroptosis through modulation of the HMGB1/TLR4 pathway." (PMID 42004898, 2026). "However, despite its proviral role in viral replication, we found that HMGB1 levels decreased in late stages of infection due to transcriptional downregulation." (PMID 40919947, 2025). "It is now known that HMGB1 secretion can be induced by infection as well as by endogenous stimuli." (PMID 40367285, 2025). "During infection, LPS-induced KLF4 expression can promote IL-10 release, particularly in the early course of infection, while later it may contribute to the release of high mobility group box 1 protein (HMGB1), a rather pro-inflammatory mediator." (PMID 40313940, 2025). "Furthermore, we validated the localization of several host proteins to viral RCs using immunofluorescence microscopy and immunoblotting and identified cellular HMGB1 as a proviral factor late during infection." (PMID 39611842, 2025). "Immunogenic cell death signatures persisted throughout infection with sustained HMGB1 elevation." (PMID 41568347, 2025). "In both tert-immortalized human corneal epithelial (THE) cells and primary human corneal epithelial cells (PCEC) infected with the highly virulent EKC virus HAdV-D37, HMGB1 in cell nuclei translocated to the cytoplasm by 24 h post-infection (hpi), and then to cell supernatants." (PMID 40367285, 2025). "Notably, HMGB1 cytoplasmic translocation also occurred with infection by HAdV-D9, earlier reported to have corneal epithelial cell tropism due to evolutionary pressure on a single amino acid at position 240 in the fiber knob." (PMID 40367285, 2025). "In this study, HMGB1 was found to be associated with SIRS in children with ALL without apparent clinical infection." (PMID 40868835, 2025). "Baicalin alleviates NOD-like receptor pyrin 3 inflammasome (NLRP3) and NF-κB signaling in piglet mononuclear phagocytes during GPS infection and inhibits the release of high mobility group box 1 (HMGB1) protein in peripheral blood monocytes induced by GPS infection." (PMID 40867785, 2025). "For instance, infection with Staphylococcus pseudintermedius activates the NLRP3/HMGB1/ROS/GSDMD signaling axis in corneal epithelial cells, exacerbating apoptosis and leading to the formation of characteristic focal holes, numerous extracellular bubbles, and other localized phenomena." (PMID 40688353, 2025). "However, during infection, necrosis, or apoptosis, HMGB1 levels rise significantly, leading to severe inflammation, epithelial barrier disruption, organ dysfunction, and even death." (PMID 40688353, 2025). "Additionally, HMGB1 is increasingly recognized as a key DAMP molecule actively released by immune cells or passively released from dying cells during infection or sterile inflammation." (PMID 40166006, 2025). "As we observed that HMGB1 can localize to RCs, we hypothesized that DBP might also interact with HMGB1, causing its relocalization during HAdV-C5 infection." (PMID 39611842, 2025). "In addition, a significant increase in the level of released high-mobility group box-1 (HMGB-1) was also detected in all SS cell lines at 72 h post infection with MV-s-NAP." (PMID 41235176, 2025). "As a response to infection, HMGB1 acts as a pro-inflammatory cytokine that may lead to cell and tissue damage." (PMID 40054422, 2025).